MAP2K6 (mitogen-activated protein kinase kinase 6)
Diseases named in the same sentence as MAP2K6 in open-access papers:
MAP2K6 is named in the same sentence as 92 diseases in open-access papers, as found by Europe PMC text mining. Sharing a sentence is not in itself a finding about the gene and the disease. The quoted sentences say what the papers report.
Obesity (14 papers, 2015 to 2024). Accumulation of substantial excess body fat. "Using significant RMR genes related to obesity founded by GWAS, such as MAP2K6 and DNAJC6, we identified various factors affecting RMR-based child obesity." (PMID 39771044, 2024). "In a previous pilot GWAS study conducted on pediatric obesity patients, DNA screening was applied to identify the SNPs (Single nucleotide polymorphism, rs9916229, rs756942) on mitogen-activated protein kinase, kinase 6 (MAP2K6, MEK6), which are correlated with RMR and obesity prevalence." (PMID 34948353, 2021). "In the pilot GWAS, we found that the MAP2K6 (MEK6, Ch#17) gene was related to RMR in children with obesity." (PMID 33540643, 2021). "One recent study showed that mice lacking Map2k6 were protected against HF‐induced obesity, possibly due to increased energy expenditure and higher Ucp1 expression in adipose tissue." (PMID 33417276, 2021). "Our pilot GWAS reported that two genes, mitogen-activated protein kinase, kinase 6 (MAP2K6) and DnaJ Heat shock Protein Family Member C6 (DNAJC6), were distinguishingly related to both the resting metabolic rate (RMR) and body mass index (BMI) as biomarkers of obesity in children." (PMID 35456010, 2022).
cardiac hypertrophy (7 papers, 2012 to 2025). "While Map2k6–/– mice have no known vascular phenotype, they have been reported to develop cardiac hypertrophy after 6 months of age in the BL6 background." (PMID 39836470, 2025).
colon cancer (7 papers, 2012 to 2023). "We identified loss-of-function uORF mutations in EPHB1 in two samples derived from breast and colon cancer, and in MAP2K6 in a sample of colon adenocarcinoma." (PMID 29402903, 2018). "MAP2K6 is overexpressed in esophageal, stomach, and colon cancer 41 and increased expression has been observed in prostate cancer upon progression." (PMID 37705754, 2023). "MAP2K6 expression is found to be significantly upregulated in gastric cancer, colon cancer, and esophageal cancer compared with the control." (PMID 32977823, 2020).
breast cancer (6 papers, 2011 to 2025). A primary or metastatic malignant neoplasm involving the breast. "Epigenetic silencing of the Synemin tumor suppressor gene (SYNM) in breast cancer is associated with poorer survival, lymph node involvement and advanced tumor grade MAP2K6 was a member of a four gene-panel used to predict prognosis in bladder cancer." (PMID 27633254, 2016). "In our study, we found that MAP2K6 had a higher expression in the better DFS group compared with the poor DFS group, which indicated that high expression of MAP2K6 may be associated with good prognosis breast cancer." (PMID 32977823, 2020). "While PGK1 is a well-characterized glycolytic enzyme with established links to tumor metabolism and hypoxia responses, MPHOSPH10 and MAP2K6 have received comparatively less attention in breast cancer." (PMID 40308601, 2025). "Further studies are needed to investigate the specific mechanisms of MAP2K6 in the prognosis of breast cancer." (PMID 32977823, 2020). "MAP2K6, a key kinase in the p38 MAPK pathway, is associated with stress and inflammatory signaling and has been linked to immune evasion and tumor progression in several cancers, including breast cancer." (PMID 40308601, 2025). "APOL3, APOL4, NR1H3, OSBPL1A, MAP2K6, and ZDHHC8 were protective genes for breast cancer prognosis." (PMID 35919504, 2022). "ABCA3, CCL22, FOXJ1, IL1RN, and MAP2K6 may serve as good prognostic factors, while KCNIP3 and MRPL13 may be poor prognostic factors for the prognosis of breast cancer." (PMID 32977823, 2020). "In conclusion, ABCA3, CCL22, FOXJ1, MAP2K6, and IL1RN may serve as good prognostic factors, while KCNIP3 and MRPL13 may be poor prognostic biomarkers to predict the recurrence and prognosis of breast cancer." (PMID 32977823, 2020).
esophageal cancer (5 papers, 2020 to 2024). A primary or metastatic malignant neoplasm involving the esophagus. "The use of MAP2K6 inhibitors can suppress the growth of esophageal cancer cells both in vitro and in vivo." (PMID 38787149, 2024). "Several studies have demonstrated that aberrant activation of MAP2K6 is involved in specific types of cancers, including human colorectal cancer, esophageal cancer, and cervical cancer 32-34." (PMID 37705754, 2023).
Insulin resistance (5 papers, 2017 to 2024). Increased resistance towards insulin, that is, diminished effectiveness of insulin in reducing blood glucose levels. "Then, we assessed the expression of an upregulated gene map2k6 and downregulated genes cacna1c and cacna1d by insulin resistance." (PMID 34358068, 2021). "In our model, the expression of the map2k6 gene increased with insulin resistance." (PMID 34358068, 2021). "The map2k6 gene is involved in phosphorylation and activation of the p38 MAP kinase, a serine/threonine-protein kinase, and p38 MAPK is related to cellular responses to inflammatory cytokines or environmental stress, including insulin resistance." (PMID 34358068, 2021).
colorectal cancer (4 papers, 2021 to 2023). A primary or metastatic malignant neoplasm that affects the colon or rectum. "MAP2K6 was identified as a direct mediator of miR-625-3p associated oxaliplatin resistance in colorectal cancer, and it was proposed that miR-625-3p and MAP2K6 could even be used to guide treatment selection." (PMID 34683154, 2021).
esophageal adenocarcinoma (4 papers, 2022 to 2025). A malignant tumor with glandular differentiation arising predominantly from Barrett mucosa in the lower third of the esophagus. "Map2k6, plays a central role in regulating cell functions; specifically, it promotes cell proliferation, as evidenced by its essentiality in esophageal adenocarcinoma cell proliferation." (PMID 39456653, 2024). "With regard to oesophageal adenocarcinoma, depleting of MAP2K6 restrained tumour cell growth." (PMID 33372369, 2022).
gastric cancer (4 papers, 2020 to 2025). A primary or metastatic malignant neoplasm involving the stomach. "Experimental studies have revealed that mitogen-activated protein kinase 6 (MAP2K6) is a direct target of miR-1298-5p, influencing the survival and invasion abilities of gastric cancer cells through autophagy regulation." (PMID 40654572, 2025). "By using transfection to decrease the level of MAP2K6 in human gastric cancer cells, the phosphorylation of p38 can be inhibited, affecting autophagy in GC cells, inducing a G2 phase cell cycle block, and suppressing cell proliferation and migration." (PMID 38787149, 2024).
bladder cancer (3 papers, 2006 to 2025). "Expression of KDR has also been demonstrated in tumors of epithelial origin and the best rules in this study imply that the expression level of KDR is consistently lower in relation to ICAM1 and MAP2K6 when there is nodal involvement in bladder cancer." (PMID 16780590, 2006).
colorectal adenocarcinoma (3 papers, 2016 to 2022). The most common type of colorectal carcinoma. "ORM2 was founded to be associated with microglial interaction, SAA4 was identified as a rheumatoid arthritis-screening biomarker, and MAP2K6 was reported to be involved in the pathogenesis of colorectal adenocarcinoma." (PMID 32130204, 2020).
hepatocellular carcinoma (3 papers, 2020 to 2022). A malignant tumor that arises from hepatocytes. "It promotes apoptosis of hepatocellular carcinoma H22 through regulating the cell cycles, upregulating Map2k6 expression, and downregulating Bcl-2 gene expression in hepatoma cells." (PMID 35911149, 2022). "Other MAPK members have been upregulated by HMGB1 including cell division control protein 42 homolog (Cdc42)/Ras-related C3 botulinum toxin substrate 1 (Rac1)/mitogen-activated protein kinase kinase 6 (MKK6)/p38 that led to the proliferation of human rhabdomyosarcoma and hepatocellular carcinoma." (PMID 32443845, 2020).
nasopharyngeal carcinoma (3 papers, 2020 to 2025). A carcinoma arising from the nasopharyngeal epithelium. "In nasopharyngeal carcinoma, MAP2K6 was associated with LIFR‐caused radioresistance." (PMID 33372369, 2022). "Overexpression of MAP2K6 predicts a worse prognosis of patients with nasopharyngeal carcinoma." (PMID 32977823, 2020).
polycystic ovary syndrome (3 papers, 2022 to 2025). A disorder that manifests as multiple cysts on the ovaries. "CircASPH also promoted KGN cell proliferation through the miR-375/MAP2K6 axis in polycystic ovary syndrome." (PMID 35795047, 2022).
atherosclerosis (2 papers, 2021 to 2022). A disease characterized by the build-up of fatty material and calcium deposition in the arterial wall resulting in partial or complete occlusion of the arterial lumen. "Together with the observations of reduced HGF, PDGBF, MAP2K6, and QDPR, these results suggest that the novel Affibody molecule effectively blocks IL17A and attenuates circulating inflammatory markers and other atherosclerosis-associated proteins." (PMID 35282365, 2022).
cervical cancer (2 papers, 2023 to 2024). A primary or metastatic malignant neoplasm involving the cervix. "Similarly, downregulation of map2k6 inhibits the MAPK pathway, reducing the proliferation and invasion of cervical cancer cells." (PMID 39456653, 2024).
heart failure (2 papers, 2014 to 2023). Inability of the heart to pump blood at an adequate rate to meet tissue metabolic requirements. "In addition, genes like MAP3K9 and MAP2K6 that are essential components of the mitogen-activated protein kinase signal transduction pathways have been linked to heart failure and cardiac hypetrophy are also detected." (PMID 25255322, 2014).
viral infection (2 papers, 2009 to 2019). "However, the effect of other HPV proteins on MAP2K6 deregulation during the course of viral infection and HPV-associated lesions progression cannot be excluded." (PMID 30674977, 2019).
COVID-19 (1 paper, 2022). A disease caused by infection with severe acute respiratory syndrome coronavirus 2. "Additionally, an increase in the expression of MAP2K6, CBL and RUNX3 was observed in COVID-19-positive patients (p = 0.047; p = 0.00093; and p = 0.0044, respectively)." (PMID 36298734, 2022). "Bioinformatics analyses showed upregulation of MAP2K6, CBL, RUNX3, STAT1, and JAK2 in COVID-19-positive vs. -negative patients." (PMID 36298734, 2022).
epilepsy (1 paper, 2015). A brain disorder characterized by episodes of abnormally increased neuronal discharge resulting in transient episodes of sensory or motor neurological dysfunction, or psychic dysfunction. "Our results showed that IRAK1 (P = 1.04 × 10−7), the targets of miR-146a, MAPKBP1 (P = 10.44 × 10−7) and CASP6 (P = 0.001), targets of miR-106b, were down-regulated, whereas MAP2K6 (P = 5.30 × 10−5), target of miR-194-5p, was up-regulated in epilepsy patients compared with normal controls." (PMID 25825351, 2015).
Myocardial fibrosis (1 paper, 2021). "While a number of exosome-derived miRNAs contribute to myocardial fibrosis, others, such as miR-378 tend to exhibit a protective effect by targeting mitogen-activated protein kinase kinase 6 (MKK6) to suppress p38 mitogen-activated protein kinase phosphorylation in cardiac fibroblasts." (PMID 33614663, 2021).
Parkinson disease (1 paper, 2023). A progressive degenerative disorder of the central nervous system characterized by loss of dopamine producing neurons in the substantia nigra and the presence of Lewy bodies in the substantia nigra and locus coeruleus. "For example, MAP2K6 is elevated in focal adhesion, adhesion, long-term potentiation, vascular smooth muscle contraction, GnRH signaling pathway, pathways in cancer, but its expression decreased in Parkinson disease, oxidative phosphorylation, phenylalanine metabolism." (PMID 36969076, 2023).
peripheral T-cell lymphoma (1 paper, 2024). "In addition, phosphatidylinositol-4,5-bisphosphate 3-kinase catalytic subunit delta (PIK3CD), mitogen-activated protein kinase kinase kinase 7 (MAP3K7) and mitogen-activated protein kinase kinase 6 (MAP2K6) are downregulated in peripheral T-cell lymphoma during chemotherapy resistance." (PMID 38468267, 2024).
prostatic intraepithelial neoplasia (1 paper, 2024). "Increased levels of MAP2K4, MAP2K6, and MAP2K7 in mouse prostate TRAMP model and tissues from patients with high-grade prostatic intraepithelial neoplasia." (PMID 39717752, 2024).
thyroid (1 paper, 2025). "In the comparison between PTC and benign thyroid samples, SFN and CCNA1 were significantly upregulated, whereas FOS, HSPA5, JUN, CREB1, and MAP2K6 exhibited significant downregulation, supporting the findings obtained from the RT-qPCR analysis." (PMID 40722651, 2025).
vascular Ehlers Danlos syndrome (1 paper, 2025). "A genetic variant in Map2k6 affords significant protection from death due to aortic rupture in a mouse model of vascular Ehlers Danlos syndrome." (PMID 39836470, 2025).
cancer (27 papers, 2011 to 2025). A tumor composed of atypical neoplastic, often pleomorphic cells that invade other tissues. "A positive correlation between the expression of APEX1 and MAP2K6 was noted, and overexpressing MAP2K6 overcame cancer-related phenotypes associated with APEX1 silencing." (PMID 36205565, 2022). "At present, it is believed that MAP2K6 may be associated with the occurrence and progression of tumors and could be potentially treated as a new diagnostic or prognostic biomarker for cancers." (PMID 36205565, 2022). "MAP2K6 may be involved in human tumorigenesis and progression and may be considered a new diagnostic or prognostic biomarker for cancer." (PMID 35919504, 2022). "Recent studies have found that MAP2K6 may be associated with the progression of cancers." (PMID 32977823, 2020). "Yin and colleagues stratified BC patients into high and low risk cancers based on a seven gene expression assay (BATF, CD3D, HLA-DQB2, JUN, MAP2K6, NFKBIE, PAK1)." (PMID 40148963, 2025). "We show that depletion of the MiDAC complex in a cancer cell line results in upregulation of the kinases MAP2K6 and MAP2K3." (PMID 41290615, 2025). "MAP2K6, a cancer-related gene, was consistently upregulated in both buccal and blood samples following vaping." (PMID 33809907, 2021). "The possible reason is that the expression of MAP2K6 in different cancers is different, and its function is complicated." (PMID 32977823, 2020). "The reduced expression of the MAP2K6 gene in the malignant sample group (group 2) and in the PTC samples group (group 4) compared to the group of normal and benign samples (group 1) suggests that this gene could serve as a diagnostic marker in malignant neoplasms." (PMID 40722651, 2025). "MAP2K6, also known as MKK6, is a key factor in MAP2K6-p38 signaling and is related to cancer cell proliferation, cell cycle progression, and tumorigenicity." (PMID 37705754, 2023). "Next, we found copy number variations of MAP2K6, SHC1, and RAC1 in most cancer tissues." (PMID 36969076, 2023). "However, it is not known whether MAP2K6 plays a role in NSCLC development by either promoting or suppressing cancer." (PMID 37705754, 2023).
tumor (24 papers, 2010 to 2026). "Among the tumor genes, we note some that have been implicated in mTOR activation (MAP2K6 and IL17RC) or inhibition (GJB3) and were upregulated or downregulated, respectively, in everolimus-adapted (LT) tumors." (PMID 39541354, 2024). "We first examined the tumor/normal differential expression of MAP2K6 by qRT-PCR assays in 60 paired NSCLC samples and paracancerous tissues." (PMID 37705754, 2023). "According to engaged studies, MAP2K6 was crucial to tumour cell growth, division and inflammation response." (PMID 33372369, 2022). "We found that MAP2K6, MAP3K5, MAP3K9, MAP3K12, RPS6KA2, RPS6KA5, and STAT1 were lowly expressed in tumor tissues; However, NFKB1, RAC1, SHC1, and TRAF2 are highly expressed compared to normal tissues." (PMID 36969076, 2023). "The functions of these genes, namely CD40, MAP2K6, TRAF5, PI3K2R, have been reported in enhancing cell proliferation and tumor growth/metastasis." (PMID 31349612, 2019). "Conversely, the significant downregulation of MAP2K6, ABCC2, and MDGA suggests impaired MAPK signaling, which may affect tumor cell proliferation, differentiation, and drug resistance." (PMID 40061903, 2025). "Indeed, although not reaching significance, we found that MAP2K6 was negatively correlated with miR-625-3p expression in 26 mCRC tumours (Pearson's r=−0.22)." (PMID 27526785, 2016).
infection (5 papers, 2016 to 2025). The state of being infected such as from the introduction of a foreign agent such as serum, vaccine, antigenic substance or organism. "In the present study, map2k6 was downregulated in fish subjected to the pathogen infection." (PMID 39456653, 2024). "These signaling pathways showed that, after LPS infection, several DEGs were mainly related to immune function, such as up-regulated expression of CCL5, IL8, NFKBIA, TRAF3, and TNFAIP3, and down-regulated expression of MEF2C, MAP2K6, TLR1, TLR2, and IRF5." (PMID 34067819, 2021). "In NHBE and THP-1 cells, five mitogen-activated protein kinase (MAPK) family members (MAP2K3, MAP2K6, MAPKAPK2, MAPKAPK3, MAPKAPK5) showed decreased activity or no significant change during pH1N1 infection, and increased activity during H3N2 and H5N1 infection." (PMID 37758692, 2023).
metabolic disease (1 paper, 2021). A congenital disorder (due to inherited enzyme abnormality) or acquired (due to failure of a metabolically important organ) disorder resulting from an abnormal metabolic process. "In contrast, we found that hepatic overexpression of Map2k6 reduced adiposity, and plasma glucose and insulin, indicating that liver regulation of Map2k6 may be pivotal for metabolic disease development." (PMID 33417276, 2021).
MAP2K6 also shares sentences with these, for which no sentence is quoted: Alzheimer disease (3 papers); Hyperglycemia (3); osteosarcoma (3); Arthritis (2); melanoma (2); neurodegenerative disease (2); prostate carcinoma (2); rheumatoid arthritis (2); Sepsis (2); acute kidney injury (1); alcohol liver disease (1); Allergy (1); Aortic dissection (1); chronic gastritis (1); colitis (1); colon adenocarcinoma (1); diabetes (1); dilated cardiomyopathy (1); endometrial cancer (1); esophageal squamous cell carcinoma (1); gingival hyperplasia (1); glioblastoma (1); glioma (1); hemangioma (1); Hyperinsulinemia (1); hyperlipidemia (1); Hypertension (1); hyperthyroidism (1); hypertrichosis (1); hypertrophy (1).
A further 32 diseases each share a sentence with MAP2K6 in 1 paper.